AR (androgen receptor)
Diseases named in the same sentence as AR in open-access papers (continued):
Sharing a sentence is not in itself a finding about the gene and the disease.
prostate carcinoma (continued). "Depletion of FOXA1 in a prostate cancer cell line (LNCaP) using small interfering RNA (siRNA) significantly inhibited AR activity, led to cell-growth suppression, and induced G0/G1 arrest." (PMID 22879989, 2012). "The transition of prostate cancer to the hormone refractory state is a major turning point in the progression of prostate cancer, and AR plays a major role in this transition." (PMID 23056316, 2012). "Recent advances in high throughput technologies such as ChIP-Chip and ChIP-Seq have enabled genome-wide identification of the AR cistrome in a number of preclinical models of prostate cancer." (PMID 22849360, 2012). "At the cell level, IL8 promotes the transition of prostate cancer to the hormone-refractory prostate cancer (HRPC) state via induction of androgen receptor expression and activation." (PMID 23213321, 2012). "In summary, studies of human prostate cancer have demonstrated basal cells, within which the α2β1HI CD133+VE stem cell resides, are efficient targets of prostate cancer initiation and that AR expression is required." (PMID 23145034, 2012). "Here we investigated both the effects of mTOR inhibition alone, as well as in combination with AR blockade, in models of prostate cancer." (PMID 22614157, 2012). "The EGFR, AR and T-cell receptor, as well as several classes of G-protein coupled receptors appeared to be significantly altered during prostate cancer initiation, the transition from primary to metastatic prostate cancer, and in case of disease recurrence." (PMID 23185449, 2012). "Specifically, in prostate cancer cells, AR signals upregulate EGFR and ERBB2 gene expression, whereas activation of EGFR and ERBB2 modulates AR functions." (PMID 22922989, 2012). "The TMPRSS2 promoter has been investigated in various prostate cancer cell lines, where it has been shown to be highly expressed in luminal cells and positively regulated by androgen receptor." (PMID 22860005, 2012). "As two examples, estrogen receptor (ER) and androgen receptor (AR) are well-known nuclear receptors that are strongly involved in breast cancer and prostate cancer, respectively." (PMID 22666069, 2012). "Pathway analysis confirmed activation of androgen receptor (AR) signaling pathways, which are known to be central to prostate cancer biology." (PMID 23145101, 2012). "In prostate cancer, aggressive cases over-express Tip60 which functions as an androgen receptor co-activator via direct acetylation of lysine residues within the KLKK motif of the receptor hinge region." (PMID 23056207, 2012). "Recently, a series of Py-Im polyamides have been developed to disrupt androgen receptor (AR) signaling, presenting an alternative strategy for therapeutic intervention in prostate cancer." (PMID 22907527, 2012). "Inhibition of AKT using siRNAs or a pharmacological inhibitor induced apoptosis in combination with bicalutamide or MDV3100 in AR-dependent prostate cancer cells." (PMID 22509301, 2012). "Specifically, we found that protein stability of androgen receptor is regulated by physiological activation of Cdk5 in prostate cancer cells and cell proliferation is, therefore, promoted." (PMID 23304206, 2012). "First, the effect of salinomycin on the expression of key genes involved in prostate cancer, AR, ERG and MYC was studied." (PMID 22215106, 2012). "Several molecular biomarkers of key prostate cancer pathogenic pathways including Ki-67 (proliferation), Bcl-2(apoptosis), CD31 (angiogenesis), Her-2/neu (oncogene), PTEN (anti-oncogene), and AR (androgen receptor) were also involved in this study." (PMID 23077456, 2012). "In the prostatic luminal epithelium, AR regulates differentiation and proliferation, and AR in prostate cancer cells promotes cell cycle progression." (PMID 22509301, 2012). "One of the conflicts with this model is that cancer stem cells have been described to lack androgen receptor (AR) expression, which is of established importance in prostate cancer initiation and progression." (PMID 23145034, 2012).
prostate carcinoma (continued). "The fact that NO is able to inhibit the canonical WNT-pathway in different tumor cells including prostate cancer cells (as seen in this study) offers a more intriguing explanation for the massive down regulation of AR and AR-V in 22Rv1 cells." (PMID 22462810, 2012). "To summarize, we present here a new cell line to study the effect of truncated AR on the progression of prostate cancer to an androgen depletion independent disease." (PMID 23209612, 2012). "CXCL8 promotes progression to castrate-resistance through ligand-independent activation of the androgen receptor (AR) and induces the proliferation of metastatic prostate cancer cells." (PMID 22590561, 2012). "It has also been shown that Src mediates EGF-induced AR tyrosine phosphorylation in prostate cancer cells, which leads to an increase in AR transcriptional activity." (PMID 22922989, 2012). "For example, prostate cancer cell line growth is inhibited by α-tocopheryl succinate by suppressing androgen receptor expression, prostate-specific antigen, and cell cycle regulatory elements." (PMID 22792240, 2012). "B-DIM induced apoptosis and inhibited cell growth, angiogenesis, and invasion of prostate cancer cells, which is associated with regulation of Akt, NF-κB, VEGF and AR signaling pathways." (PMID 23056607, 2012). "Further research is required to fully characterize the effect of the AR on the role of miR-370 in prostate cancer progression, and the role of miR-370 in the development of androgen independence." (PMID 23029264, 2012). "LAPC4 prostate cancer cells express wild type AR, reflecting the AR status of most androgen dependent prostate cancers." (PMID 23056316, 2012). "Recent reports have identified previously unappreciated crosstalk in prostate cancer cells between the AR pathway and PI3K signalling pathway, the major signalling pathway activated downstream of the INSR." (PMID 22548055, 2012). "As previously human prostate stem cells were considered to lack AR, the characterisation of AR expression within α2β1HI CD133+VE cells offers a resolution to a key paradox about the cell of origin in prostate cancer." (PMID 23145034, 2012). "There is experimental evidence that the WNT/β-catenin-pathway is able to up-regulate AR-mRNA expression in prostate cancer cell lines through interaction with TCF/LEF binding sites situated in the promoter region of the AR." (PMID 22462810, 2012). "It interacts with AR and promotes prostate cancer cellular growth and proliferation by activating AR transcription in an androgen-dependent manner." (PMID 23231703, 2012). "Since the COUP-TF II overexpression inhibits the androgen-dependent growth of LNCaP prostate cancer cells, we investigated a possible cross-talk between COUP-TF II and AR, which is important for the development of prostate cancers." (PMID 23145053, 2012). "Bicalutamide treatment resulted in significant suppression of PSA levels and moderate decrease of AR expression in both LNCaP and C4-2 prostate cancer lines." (PMID 22614157, 2012). "Compensatory regulation between the AR and mTOR pathways has emerged as a key mechanism in the pathogenesis of prostate cancer." (PMID 22614157, 2012). "In the present study, we demonstrate that COUP-TF II represses the transactivation of AR in prostate cancer cells, resulting in the inhibition of androgen-dependent cell growth." (PMID 23145053, 2012).
prostate carcinoma (continued). "Activation of AMPK by B-DIM results in the suppression of its downstream target mTOR, down-regulation of AR expression and induction of apoptosis in both androgen-sensitive LNCaP and androgen-insensitive C4-2B prostate cancer cells." (PMID 23056607, 2012). "The signaling pathways regulating prostate cancer cell growth and AR activity play a pivotal role in the transition from androgen-dependent prostate cancer to castration-resistant disease." (PMID 22761715, 2012). "The androgen receptor plays a central role in prostate cancer pathogenesis and survival so there is strong selective pressure to retain mutations that lead to activity in the face of anti-androgen therapies." (PMID 22389719, 2012). "The confirmation of AR expression in prostate progenitor cells allows integration of the cancer stem cell theory with the established models of prostate cancer initiation based on a functional AR." (PMID 23145034, 2012). "Recent studies suggest that taxane chemotherapy in prostate cancer can impede AR translocation from the cytoplasm to the nucleus by disrupting microtubules that normally function to transport AR to the nucleus." (PMID 23087897, 2012). "One of the current treatment strategies for advanced prostate cancer is to suppress AR function by castration and anti-androgens." (PMID 23056607, 2012). "Continued androgen receptor (AR)-signalling remains the dominant growth pathway in prostate cancer progressing under low levels of circulating androgens." (PMID 23109869, 2012). "In this work, QSAR and docking studies of androgen receptor antagonists with anticancer activity against human prostate cancer cell line LNCaP were carried out." (PMID 22754355, 2012). "FoxA1, also known as hepatocyte nuclear factor HNF-3-alpha, is a key partner for ERα and AR in promoting transcriptional activity in breast and prostate cancer, respectively, and recognizes the FKH motif." (PMID 22383394, 2012). "Androgen-deprivation therapy (ADT) is a common treatment for prostate cancer, as the androgen receptor (AR) plays a role in the development of this malignancy." (PMID 25031959, 2012). "Molecular studies using specific FISH probes on CTCs from advanced prostate cancer patients have noted gains in AR and MYC, losses in PTEN, and evidence for ERG gene rearrangement." (PMID 22373240, 2012). "Due to the function of AR as an important oncogene in prostate cancer, the effect of AIM1, ERGIC1, TMED3, and TPX2 expression on AR signaling was analyzed." (PMID 22761906, 2012). "The ZNF652 (17q21.32) locus codes for a DNA binding protein thought to act as a tumor suppressor gene in breast cancer that is also co-expressed with the androgen receptor in prostate cancer." (PMID 22829776, 2012). "Despite the fact that both NcoA4α and β function as AR coactivators in cell-based reporter assays, full-length NcoA4 suppressed androgen-induced proliferation of AR-expressing prostate cancer cell lines in vitro and in vivo." (PMID 22562579, 2012). "Of these compounds, two hairpin polyamides developed to disrupt AR signaling are of particular interest due to their gene regulation activities and potent cytotoxicity toward the LNCaP prostate cancer cell line." (PMID 22907527, 2012). "GSE is also protective against prostate cancer which was shown to inhibit histone acetyltransferases (HATs) in LNCaP cells, leading to decreased androgen-receptor- (AR-) mediated transcription and cancer cell growth." (PMID 22919383, 2012). "Several studies indicate that NcoA4 localizes predominantly to the cytoplasm and affects ligand-binding specificity of the androgen receptor, which has important implications for androgen-independent prostate cancer." (PMID 22562579, 2012). "Previous work in our laboratory shows that this increased AR level is necessary and sufficient for the progression of prostate cancer to CRPC and its function is essential to sustain tumor growth." (PMID 22509301, 2012).
prostate carcinoma (continued). "Alternative mechanisms of AR activation in androgen-independent prostate cancer are proposed through other signaling pathways, including ERKs, Akt, β-catenin and caveolin." (PMID 23056607, 2012). "The regulation of TMPRSS2 by AR has been shown directly in a limited number of AR+ luminal prostate cancer cell lines and indirectly in primary prostate cancers where TMPRSS2 expression correlates with expression of other AR-regulated genes." (PMID 22860005, 2012). "EGF has been shown to enhance the expression or phosphorylation of TIF2, one of the p160 nuclear receptor coactivators, leading to an increase in AR transactivation in prostate cancer cells." (PMID 22922989, 2012). "If the prostate stem cell is the cell of origin for transformation, then this model appears to be at odds with the emerging mechanisms of prostate cancer development and progression dependent upon AR signalling." (PMID 23145034, 2012). "Despite the determining role played by the androgen receptor in all stages of prostate cancer progression, there is a conspicuous dearth of comparable data on the consequences of mutations." (PMID 22403669, 2012). "When we examined prostate cancer bone metastases in patients the cancer cells were growing in a fibroblast like stroma with less smooth muscle actin and AR expression and more SDF-1 expression than in the corresponding primary tumor stroma." (PMID 24213323, 2012). "Our analyses show that qualitative and quantitative assessment of chromatin accessibility by DNase-seq is an important and useful tool for elucidating AR biology in prostate cancer cell line models." (PMID 23034120, 2012). "We showed in the present study that co-treatment of cells with casodex and B-DIM led to a significant increase in phosphor-AMPKα and suppressed AR expression in prostate cancer cells, demonstrating a novel mechanism for synergy of anti-AR therapy." (PMID 23056607, 2012). "Given the critical role of AR in prostate cancer progression and particularly the late stages of the disease, additional therapeutic approaches are under development to target the receptor." (PMID 22849360, 2012). "The androgen/AR signaling pathway is demonstrated to play a central role in prostate cancer development and progression." (PMID 23231703, 2012). "Androgen receptor (AR) controls cell proliferation and survival in the normal prostate and prostate carcinomas (PCa)." (PMID 22879924, 2012). "In the present study, we have shown that COUP-TF II modulates AR function in prostate cancer cells, affecting androgen-dependent cell proliferation." (PMID 23145053, 2012). "Recent studies identifying putative truncated androgen receptor isoforms with ligand-independent activity have shed new light on the acquisition of androgen depletion independent (ADI) growth of prostate cancer." (PMID 23209612, 2012). "AR plays an important role in normal prostate development and maintenance, and in prostate cancer progression." (PMID 22666381, 2012). "The androgen receptor plays a critical role throughout the progression of prostate cancer and is an important drug target for this disease." (PMID 22849360, 2012). "Prostate cancer is dependent on androgen stimulation mediated by AR, and AR even plays an important role in cancer development and drug-resistance in androgen-independent prostate cancer cells." (PMID 23056607, 2012). "Casodex is an anti-androgen drug clinically used for patients with metastatic/advanced stage prostate cancer, and works by binding and preventing the activation of the AR." (PMID 23056607, 2012). "VCaP is a model for TMPRSS2-ERG positive prostate cancer, expressing wild type AR, whereas LNCaPs harbour a mutant AR (T877A) with extended ligand specificity." (PMID 22761906, 2012). "The androgen receptor (AR), a master regulator of the male phenotype and prostate cancer pathogenesis, acts primarily through ligand-activated transcription of target genes." (PMID 23034120, 2012).
prostate carcinoma (continued). "Second, the historical success of targeting AR for prostate cancer provides a proof of principle for its use as a target in cancer therapy." (PMID 22321971, 2012). "At a concentration of 2 μM PTS33 effectively suppressed the growth of AR-positive prostate cancer (PCa) cells, and had little effect on AR-negative PCa cells." (PMID 23202971, 2012). "In some prostate cancer cell lines, certain AR antagonists can serve as agonists, probably due to the presence of a mutant AR." (PMID 23056316, 2012). "Because EGF was shown to induce AR transcription by upregulating TIF2 expression in prostate cancer cells, we then determined the levels of TIF2 expression in bladder cancer cell lines upon treatment with EGF, androgen and/or antiandrogen." (PMID 22922989, 2012). "TCF3 is involved in the Wnt/β-catenin signaling pathway, which crosstalks with AR signaling in prostate cancer." (PMID 23034120, 2012). "The profound differences in local NO-production prompted us to analyze the effects of JS-K on the AR-concentration in the prostate cancer line 22Rv1 and LNCaP." (PMID 22462810, 2012). "Together, these results indicate that COUP-TF II represses AR function in prostate cancer cells, inhibiting the expression of endogenous AR target gene PSA." (PMID 23145053, 2012). "We identified and validated four candidate genes (AKT1, PSMC1, STRADA, and TTK) that impaired growth when silenced in androgen receptor positive prostate cancer cells and enhanced the antiproliferative effects of antiandrogens." (PMID 22509301, 2012). "Pathway analysis results provide additional verification of these findings, as the “Androgen Receptor Signaling Pathway” and “Fatty Acid Biosynthesis” appeared to be significantly altered during prostate cancer initiation." (PMID 23185449, 2012). "In AI prostate cancer cells, Akt takes over the role of AR and more effectively contributes through the same signaling molecule, beta-catenin, to AI cancer progression." (PMID 23455493, 2012). "We have been studying formulated 3,3′-Diindolylmethane (B-DIM) and showed that B-DIM can induce apoptosis and inhibit cell growth, angiogenesis, and invasion of prostate cancer cells by regulating NF-κB, Akt and AR signaling pathways." (PMID 23056607, 2012). "AIM1, ERGIC1, and TPX2 were shown to be highly expressed especially in prostate cancer tissues, and high mRNA expression of ERGIC1 and TMED3 associated with AR and ERG oncogene expression." (PMID 22761906, 2012). "We have previously shown that activation of the MAP kinase pathway correlates with prostate cancer progression in a variety of settings and determined that stress kinase signaling regulates AR Ser 650 phosphorylation." (PMID 22761715, 2012). "In order to gain information on AR's activity in androgen dependent prostate cancer a bioinformatical analysis of AR target genes was performed." (PMID 23056316, 2012). "In our study, BR-DIM (BioResponse, 3,3′-Diindolylmethane) treatment for prostate cancer resulted in the demethylation of the promoter of miR-34a, which inactivates androgen receptor." (PMID 22970379, 2012). "The relationship of the AR and its functionality to currently researched prostate cancer biomarkers is an area resounding with promise." (PMID 22641253, 2012). "Hypermethylation of these CGI have been shown to silence AR transcription in prostate cancer cells and primary tumours." (PMID 22471922, 2012). "Inhibition of AKT with a pharmacologic inhibitor also induced apoptosis when combined with antiandrogens, consistent with recent evidence for PI3K and AR pathway crosstalk in prostate cancer cells." (PMID 22509301, 2012).